SDC1 (syndecan 1)
Diseases named in the same sentence as SDC1 in open-access papers (continued):
Sharing a sentence is not in itself a finding about the gene and the disease.
endometrial cancer (10 papers, 2010 to 2025). Primary or metastatic malignant neoplasm involving the endometrium (mucous membrane that lines the endometrial cavity). "Loss of epithelial syndecan-1 expression and induction of stromal syndecan-1 expression are associated with reduced survival in patients with endometrial cancer." (PMID 26420915, 2015). "Syndecan-1 seems to be early in the signal cascades necessary for the onset of endometrial cancer progression." (PMID 26420915, 2015). "Upregulation of syndecan-1 in a xenograft model leads to the development of proliferative and invasive/metastatic phenotypes in endometrial cancer." (PMID 26420915, 2015). "Studies in endometrial cancer showed that upregulated Sdc-1 promotes the viability of the cells via activation of NFκB whereas silencing of Sdc-1 induced apoptosis correlated with a decrease in the activation of MAPK Erk and Akt." (PMID 25830352, 2015). "Recent studies focused on Sdc-1's role in promoting tumour invasion in endometrial cancer cell lines in-vitro via nuclear factor-kappaB (NF-κB) signalling." (PMID 21044331, 2010). "It was shown that SDC1 promotes tumor growth and angiogenesis in endometrial cancer cells." (PMID 32756007, 2020). "Furthermore, nuclear factor kappa B (NFκB) was found to be an important mediator of Syndecan-1 (Sdc-1) action during the tumour growth and invasiveness of endometrial cancer." (PMID 28293067, 2017). "Former studies showed an involvement of Sdc-1 in MMP-9 regulation, a main target of TIMP-1, mediating endometrial cancer invasion." (PMID 21044331, 2010). "Moreover, SDC1 expression was totally absent in poorly differentiated endometrial cancer tissues, while it was abundant in normal endometrial and highly differentiated malignant tissues." (PMID 26293675, 2015).
lymph node metastasis (10 papers, 2008 to 2023). "We found SDC1 was significantly associated with overall survival, and lymph node metastasis in TCGA database." (PMID 37069585, 2023). "SDC1 expression was also associated with lymph node metastases and aggressive progression after surgery." (PMID 26293675, 2015). "Epithelial expression of syndecan-1 negatively correlates with lymph node metastasis and associates with a longer survival, whereas stromal syndecan-1 expression associates with a shorter survival." (PMID 26420915, 2015). "Epithelial SDC1 was observed in approximately half of gallbladder cancer cases evaluated, and its expression was associated with lymph node metastasis." (PMID 26293675, 2015). "SDC1 is key in maintaining the survival and development of cancer cells, and SDC1 expression has been related to tumor differentiation, depth of invasion, lymph node metastasis, distant metastasis, TNM stage, and prognosis." (PMID 35672673, 2022). "Reduced expression of syndecan-1 is correlated with poor histological differentiation, lymph node metastasis, and poor prognosis after surgical resection." (PMID 26420915, 2015). "Besides, the expression difference of SDC1 between lymph node metastasis groups was statistically significant." (PMID 35793235, 2022). "However, in female patients, SDC1 serum levels were significantly increased (p = 0.026), moreover, SDC1 baseline values were significantly correlated with the presence of lymph node metastases as well (p = 0.026)." (PMID 33114033, 2020). "Thus, circulating levels of SDC1 may ultimately be a useful prognostic tool for identifying patients with lymph node metastases." (PMID 26293675, 2015). "The incidence of low expression of syndecan-1 was significantly higher in males (p = 0.042), in tumors of higher TNM stage (p = 0.045), and in patients positive for lymph node metastasis (p = 0.017)." (PMID 18590537, 2008). "In approximately 90% of adenocarcinomas examined, SDC1 expression was absent, and this correlated with lymph node metastasis." (PMID 26293675, 2015). "Syndecan-1 expression was not significantly different between patients with and without lymph node metastasis (random-effects model: OR = 0.91, 95 % CI = 0.34 − 2.43) or distant metastasis (random-effects model: OR = 0.89, 95 % CI = 0.19 − 4.21)." (PMID 26518017, 2015). "This meta-analysis indicated that loss of syndecan-1 expression is associated with CRC development, histological differentiation, and clinical stage, but not with lymph node metastasis and distant metastasis." (PMID 26518017, 2015). "The results of our study demonstrate that the loss of expression of syndecan-1 from colonic epithelial cells in colorectal adenocarcinomas correlates with tumor TNM stage and incidence of local lymph node metastasis but nevertheless does not correlate statistically with patient survival." (PMID 18590537, 2008).
urothelial carcinoma (10 papers, 2015 to 2024). A malignant neoplasm derived from the transitional epithelium of the urinary tract (urinary bladder, ureter, urethra, or renal pelvis). "Finally, syndecan-1 was detected in plasmacytoid urothelial carcinoma, an aggressive tumor, demonstrating that the protein is closely associated with urothelial carcinoma progression." (PMID 26514209, 2015). "We investigated the role of heparanase, an enzyme activated by syndecan-1 in human urothelial carcinoma." (PMID 32471161, 2020). "The data show that—across all organs of origin—squamous cell (and urothelial) carcinomas are particularly prone to express Syndecan-1, often at high levels." (PMID 31976021, 2019). "MiR-145 reduces syndecan-1 and increases stem cell factors and induces cell differentiation and senescence on urothelial carcinoma cells." (PMID 30871066, 2019). "In conclusion, miR-145 utilizes syndecan-1 to modulate cell proliferation, re-programming, and differentiation in urothelial carcinomas." (PMID 26514209, 2015). "Taken together, the data suggest that miR-145 regulates cell proliferation and differentiation in urothelial carcinoma cells by down-regulating syndecan-1 while up-regulating some stem cell markers." (PMID 26514209, 2015). "We previously reported that syndecan-1 (CD138) may contribute to urothelial carcinoma cell survival and progression." (PMID 32471161, 2020). "Indeed, syndecan-1 might contribute to cell survival and progression, and is up-regulated in urothelial carcinomas, particularly in high-grade and aggressively invasive cancers." (PMID 26514209, 2015). "Based on the expression of SDC1, LUM, VEGFA, TIMP3 and WNT7B in various urothelial carcinoma cell lines in the CCL database, we selected J82 and UMUC3 as the verification cell lines, and marked them with puromycin resistance labelling." (PMID 38183115, 2024). "Moreover, miR-145 and syndecan-1 were found to be up-regulated in low-grade urothelial carcinoma, but not in high-grade tumors." (PMID 26514209, 2015).
ameloblastoma (9 papers, 2013 to 2025). The most common odontogenic tumor, arising from the epithelial component of the embryonic tooth and usually affecting the molar-ramus region of the mandible or maxilla. "The evaluation of the expression of E-cadherin and syndecan-1 are important for determining the potential aggressiveness of ameloblastoma variants." (PMID 29850393, 2018). "The loss of syndecan-1 expression in ameloblastomas and ameloblastic carcinomas has been demonstrated to correlate with more aggressive biological behaviors (invasion and metastasis)." (PMID 23476862, 2013). "Low levels of syndecan-1 expression correlate with tumor progression and development (found in multicystic ameloblastomas and AC)." (PMID 40699660, 2025). "E-Cadherin and syndecan-1 are cell adhesion molecules related to the behavior of various tumors, including ameloblastomas." (PMID 29850393, 2018). "Ninety-nine ameloblastoma samples were studied; the expression of E-cadherin and syndecan-1 were evaluated by immunohistochemistry." (PMID 29850393, 2018). "On the other hand, these authors also showed that the expression of syndecan-1 (CD138) (used as a cell adhesion marker) was also elevated, thus reflecting the scant invasive capacity of these lesions compared with unicystic ameloblastomas." (PMID 39399852, 2024). "The main aim of this study was to explore the immunoexpression of stem cell markers nestin, CD138 (syndecan-1), and alpha-SMA in a series of four cases of ameloblastic carcinoma and to compare this data to an ameloblastoma immunoexpression profile." (PMID 33917771, 2021). "The expression and distribution of maspin and syndecan-1 were immunohistochemically investigated in the OKC and compared to those in the dentigerous cyst (DC) and ameloblastoma (AB)." (PMID 32733563, 2020). "In this study, the expressions of an important regulatory protein (maspin), an important integral membrane proteoglycan (syndecan-1), and a universal proliferation marker (Ki-67) in the epithelium of the OKC were investigated in comparison with the dentigerous cyst (DC) and ameloblastoma (AB)." (PMID 32733563, 2020).
Hypertension (9 papers, 2021 to 2026). The presence of chronic increased pressure in the systemic arterial system. "While the sample size in this study is relatively modest, the findings reveal statistically significant and biologically plausible associations between serum SDC1 levels and MetS subgroups, particularly among males with combined hypertension and elevated ALT." (PMID 41039734, 2025). "These ex vivo effects on contractility were absent in syndecan-1 deficient mice in our study, suggesting that syndecan-1 is essential for sFLT1-induced hypertension." (PMID 33623064, 2021). "This review summarizes current evidence and underscores the potential of eGC shedding markers, especially syndecan 1 (SDC-1) and hyaluronic acid (HA), as early predictors of vascular risk and disease progression in hypertension and CKD." (PMID 42073452, 2026). "In conclusion, while larger studies are needed for validation, our findings provide preliminary evidence supporting SDC1's role in MetS, particularly in males with hypertension and elevated ALT." (PMID 41039734, 2025). "We also examined the disease progression and characteristics by the use of an aneurysm mouse model generated by the combination of aortic wall weakness and hypertension in SDC-1+/+ or SDC-1−/− mice on C57Bl/6J background." (PMID 35548440, 2022). "Growing evidence suggests that elevated levels of both shed SDC1 and SDC4 are associated with hypertension and cardiovascular diseases, but their relationships with cardiovascular risk factors in healthy individuals are unknown." (PMID 33668381, 2021). "In addition, the role of SDC-1 was evaluated in descending TAA in vivo using a mouse model combining both aortic wall weakening and hypertension." (PMID 35548440, 2022).
ischemia (9 papers, 2021 to 2025). A hypoperfusion of the BLOOD through an organ or tissue caused by a PATHOLOGIC CONSTRICTION or obstruction of its BLOOD VESSELS, or an absence of BLOOD CIRCULATION. "Increased shedding of syndecan-1 (SDC-1), a transmembrane proteoglycan, has been related to ischemia-reperfusion injury in clinical conditions associated with increased oxidative- and vascular shear stress causing eGCX degradation." (PMID 41152395, 2025). "Overall, shedding appeared largely independent of CVP strategy and ischemia/reperfusion status, with a late postoperative rise in syndecan-1 under LCVP in non-ischemia cases suggesting potential endothelial cost of aggressive fluid restriction/vasopressor use." (PMID 41303775, 2025). "The concentration of the soluble glycocalyx component syndecan-1 has been shown to increase in the systemic circulation even before aortic cross-clamping and the onset of ischemia." (PMID 39456673, 2024). "Syndecan-1 concentrations in systemic circulation began to increase already before aortic cross-clamping, that is, before the onset of ischemia." (PMID 37233179, 2023). "Like with syndecan-1, intermittent cardioplegia probably washed out any heparan sulfate accumulated during ischemia." (PMID 33999952, 2021). "In the case of ischemia followed by reperfusion under CPB, increased concentration of syndecan-1 and heparan sulphate can be found in the circulation." (PMID 39456673, 2024). "In patients with LVEF <45% (HFrEF), independent predictors of ischemia were BNP (p = 0.001), renalase (p < 0.001), sST2 (p = 0.004), galectin-3 (p = 0.003), GDF-15 (p = 0.001), and syndecan-1 (p < 0.001)." (PMID 34395559, 2021). "Due to the different collection of blood samples for heparan sulfate and syndecan-1, data were analyzed separately for patients with or without ischemia." (PMID 41303775, 2025). "The late postoperative rise in syndecan-1 observed in the low-CVP group without ischemia highlights the complex interplay between fluid restriction, vasopressor use, and endothelial integrity." (PMID 41303775, 2025). "CVP strategy and ischemia-reperfusion status did not consistently alter the extent of glycocalyx shedding, except for a late postoperative rise in syndecan-1 observed in the low-CVP group without ischemia." (PMID 41303775, 2025). "In our study, the choice of CVP strategy did not yield consistent differences in glycocalyx biomarkers, except for a significantly higher syndecan-1 level at T3 in the LCVP group without ischemia." (PMID 41303775, 2025). "Animal studies have shown that ischemia–reperfusion injury can result in EG shedding due to increased production of ROS and RNS or a secondary inflammatory response, leading to increased levels of syndecan-1 and heparan sulphate in the circulation." (PMID 39456673, 2024). "However, unlike the ischemia AKI model, the current glycerol AKI model evoked decreases in aortic and renal segmental artery SDC‐1 staining without any discernable loss of SDC‐1 from renal tubules, as assessed by immunohistochemistry." (PMID 39905680, 2025). "Thus, recent evidence from a rat model of heart IRI showed that although IRI undoubtedly increased the release of syndecan-1 in the coronary effluent, treatment with S1P before development of ischemia had no visible effect on syndecan-1 release." (PMID 33671524, 2021). "The late postoperative rise in syndecan-1 in the low-CVP cohort without ischemia suggests that the combination of stringent fluid restriction and compensatory vasopressor use may stress the endothelium and degrade the glycocalyx, even when overt ischemia-reperfusion is absent." (PMID 41303775, 2025).
pneumonia (9 papers, 2019 to 2023). An acute, acute and chronic, or chronic inflammation focally or diffusely affecting the lung parenchyma, caused by an infection in one or both of the lungs (by bacteria, viruses, fungi, or mycoplasma.). "Our studies on the role of syndecans in S. pneumoniae corneal infection showed that Sdc1 knockout causes a specific gain of function that enables mice to significantly resist infection." (PMID 33293379, 2020). "The strategies based on inhibiting SDC1 upregulation when giving GCs may provide new therapeutic approaches to correct the risk of pneumonia that occurs in administrating GCs in chronic lung disease." (PMID 34790176, 2021). "The levels of IL-6, procalcitonin, sRAGE, and angiopoietin-2 were lower post-event compared to the day of pneumonia diagnosis, while syndecan-1 and angiopoietin-1 concentrations were higher post-event; the other host response biomarkers remained unaltered." (PMID 37415223, 2023). "Administration of excess Sdc1 ectodomains significantly inhibited S. pneumoniae corneal infection, suggesting that Sdc1 promotes infection as a cell surface attachment receptor." (PMID 33293379, 2020). "The prominent phenotype of Sdc1−/− corneas also indicated that Sdc4 and other HSPGs do not functionally compensate for the loss of Sdc1 in S. pneumoniae corneal infection." (PMID 33293379, 2020). "Administration of FN significantly inhibited S. pneumoniae corneal infection in a dose-dependent manner, and at the highest dose tested, FN had a similar inhibitory effect as that of purified Sdc1 ectodomains where the corneal bacterial burden was decreased by more than 95% compared to control." (PMID 33293379, 2020). "In this comparison, syndecan-1 and heparan sulfate plasma concentrations are significantly higher and ADAMTS13 significantly lower in patients progressing from pneumonia to severe pulmonary failure (ARDS)." (PMID 36776845, 2023). "Regardless, our results indicate that there is no direct role for cell surface or shed Sdc1 in promoting S. pneumoniae corneal infection." (PMID 33293379, 2020). "Sdc1 does not promote S. pneumoniae corneal infection as an attachment receptor or as an inhibitor of host defense." (PMID 33293379, 2020). "However, when the test compounds were preincubated with bacteria and removed prior to infection, intact FN and Hep II fragments significantly inhibited S. pneumoniae corneal infection, but Sdc1 ectodomains did not." (PMID 33293379, 2020).
Stroke (9 papers, 2021 to 2024). Sudden impairment of blood flow to a part of the brain due to occlusion or rupture of an artery to the brain. "The longitudinal assessment of syndecan-1 levels in the peripheral blood of 37 patients at six time points showed a biphasic change after stroke occurrence, with the most significant increase observed at 1 h post-operation." (PMID 39233682, 2024). "It is worth noting that syndecan-1 plays a specific role in the pathophysiological processes at various stages of brain tissue injury after stroke." (PMID 39233682, 2024). "And it has been shown that plasma level of syndecan-1 increased in acute ischemic stroke and syndecan-1 level predicted the prognosis in stroke patients." (PMID 37196119, 2023). "The increased level of syndecan-1 at 36 h after endovascular treatment was positively correlated with the National Institute of Health Stroke Scale score for neurological deterioration (r = 0.702, p = 0.005)." (PMID 36779062, 2023). "The upregulation of Cd3d, Cd3e, Cd3g, Blnk, Sdc1, and Jchain suggests that chronic inflammation persists in peri-infarct regions for at least 7 weeks after stroke." (PMID 34819339, 2022). "GCX components hyaluronan and syndecan-1 display biphasic expression in recovery following stroke." (PMID 39125975, 2024). "The LASSO regression analysis yielded seven variables that most strongly correlated with adverse prognosis after thrombolysis in AIS, including age, NIHSS score, history of atrial fibrillation, mechanical thrombectomy, blood CRP level, stroke classification, and syndecan-1 level." (PMID 35910391, 2022).
viral infection (9 papers, 2011 to 2025). "In conclusion, using proteomic analysis we found that the DEPs SPP1, IFIT5, ISG15, VCL, and SDC1 are significantly changed in PSV-infected PK-15 cells, suggesting that these proteins may be closely related to viral infection." (PMID 32575635, 2020).
B-cell lymphoma (8 papers, 2013 to 2025). "MMPCs are late-stage B-cells expressing the characteristic markers CD138 (syndecan-1), CD38, and monoclonal Ig light-chain, but lacking the CD19 marker for pre-differentiated B-cells and other B-cell lymphomas." (PMID 38002311, 2023).